PDK2 (pyruvate dehydrogenase kinase 2)
Diseases named in the same sentence as PDK2 in open-access papers (continued):
Sharing a sentence is not in itself a finding about the gene and the disease.
rectal cancer (1 paper, 2025). A primary or metastatic malignant neoplasm that affects the rectum. "In rectal cancer, O-GlcNAc modification of c-Myc at Ser415 enhances the stability of c-Myc and increases the expression of pyruvate dehydrogenase kinase 2 (PDK2), which reduces mitochondrial pyruvate metabolism, inhibits ROS production, and promotes the growth of xenograft tumors." (PMID 41280891, 2025).
renal fibrosis (1 paper, 2021). A final common manifestation of a wide variety of chronic kidney diseases characterized by glomerulosclerosis and tubulointerstitial fibrosis. "Based on the analysis of specific genes expressed in cisplatin-induced renal fibrosis, ACAT1, GGT1, and PDK2 were predominantly expressed in tubule cells." (PMID 34777334, 2021).
steatosis (1 paper, 2018). Increased lipid within the cytoplasm of cells. "Recently, a PDK2 inhibitor targeting the ATP binding pocket was reported to improve glucose tolerance and to reduce hepatic steatosis by affecting pyruvate dehydrogenase complex activity." (PMID 30547786, 2018).
type 1 diabetes (1 paper, 2021). "Furthermore, PDK2/4 knockout mice resisted pain hypersensitivity, macrophage infiltration, satellite cell activation and loss of peripheral nerve fibres after induction of type 1 diabetes." (PMID 33592336, 2021).
tumor (44 papers, 2006 to 2025). "While DCA exhibits sensitivity to PDK2 and holds promise for augmenting cisplatin sensitivity, its clinical translation is impeded by its limited efficacy in suppressing tumor growth and the associated systemic toxicity." (PMID 39479443, 2024). "Pyruvate dehydrogenase kinase 2 (PDK2) is associated with proliferation, anti-apoptosis, tumor aggressiveness, and therapy resistance." (PMID 38202644, 2023). "TF GATA1 could positively regulate target gene PDCL3, which was modified by DNA methylation, to cause tumor cell proliferation and angiogenesis through signaling transduction protein PDK2." (PMID 31126066, 2019). "Exosomal miR-214 also inhibits tumor cell proliferation, migration, and metabolic activity by targeting Pyruvate Dehydrogenase Kinase Isoform 2 (PDK2) and PHD Finger Protein 6 (PHF6) in HCC cell cultures." (PMID 41515889, 2025). "When PDK2 expression is elevated, cell metabolism undergoes reprogramming similar to that of tumor cells." (PMID 39149122, 2024). "Dysfunction of complex I also leads to increased levels of α-ketoglutarate, alterations in Hypoxia-inducible factor-1α (HIF1α), generation of ROS, and activation of pyruvate dehydrogenase kinase 2 (PDK2), which accelerates tumor growth." (PMID 38737905, 2024). "We next explored the effects of c-Myc-mediated PDK2 expression on cell proliferation and tumor growth." (PMID 38778217, 2024). "Studies indicate that B cell receptor activation regulates B cell-derived IL-35 expression through downstream protein kinase D2 (PDK2), suppressing the immune capacity of anti-tumor T cells and fostering PC development." (PMID 38634049, 2024). "Growing evidence suggests that PDK2 influences glucose metabolism which is consequently attributed to tumor development." (PMID 38376420, 2024). "Collectively, these results demonstrate that c-Myc glycosylation-regulated PDK2 expression promotes glucose metabolism and tumor growth." (PMID 38778217, 2024). "PDK2 promotes multiple tumor drug resistance by inhibiting tumor mitochondrial function and negatively regulating macrophage polarization." (PMID 38671369, 2024). "We observed that the levels of c-Myc, PDK2 and c-Myc glycosylation were all significantly higher in tumor tissues compared to the matching peritumoral tissues." (PMID 38778217, 2024). "To further evaluate the effect on tumor growth, we generated stable HT-29 cell lines with depletion of endogenous c-Myc or PDK2, and reconstituted expression of PDK2 in c-Myc-depleted cells." (PMID 38778217, 2024). "Studies have shown that in colorectal cancer, miR-149-3p targets pyruvate dehydrogenase kinases 2 (PDK2) to promote 5-fluorouracil (5-FU)-induced apoptosis and reduce glucose metabolism within the tumor microenvironment." (PMID 39440054, 2024). "c-Myc glycosylation-mediated expression of PDK2 dampens the mitochondrial pyruvate metabolism and ROS production, leading to enhanced cell proliferation and tumor growth in mice." (PMID 38778217, 2024). "The c-Myc or PDK2 depletion similarly inhibited tumor growth and reduced Ki-67 expression in tumors." (PMID 38778217, 2024). "Pyruvate dehydrogenase kinase 2 (PDK2) is essential for cancer's glycolysis and promotes tumor growth." (PMID 37587156, 2023).
tumor (continued). "Our molecular gene profiling analysis suggests differences in the tumor microenvironment in groups of ccRCC tumors depending on PDK2/PDK3 expression." (PMID 37147361, 2023). "PDK1 and PDK2 silencing downregulated the tumor sphere formation, motility, CSC genes, and multidrug-resistant genes in HNC CSCs." (PMID 36474273, 2022). "PDK1 and PDK2 were knocked down by the lentivirus shRNA system to investigate their role in TGFβ1-promoted tumor progression in vitro." (PMID 36474273, 2022). "In this study, we discovered that PDK1 and PDK2 are metabolic checkpoints for tumor progression and CSC features under TGFβ1 modulation within the TME of HNC." (PMID 36474273, 2022). "Recent studies have tried to explore the factors influencing PD-L1 expression, and demonstrated that IFN-γ promotes PD-L1 expression on macrophage and tumor cells in a STAT1- or PDK2-dependent manne." (PMID 29593314, 2018). "In our study, PDK2 promotes tumor growth, elevates ATP production and facilitates the metabolic shift from oxidative phosphorylation to aerobic glycolysis in GC cells." (PMID 29725130, 2018). "Tumor volume and Ki67 expression were significantly increased in tumors derived from PDK2-overexpressing MGC803 cells, whereas opposing results were obtained after PDK2 deletion in SGC7901 cells." (PMID 29725130, 2018). "Consistent with that possibility, our studies showed lower PDK-1 (and PDK-2) expression in c4 tumours compared with WT." (PMID 21612605, 2011). "Multivariate analysis identified tumor volume and PDK2 expression as independent prognostic variables." (PMID 17054779, 2006). "A similar analysis based on KLF3 and PDK2 expression, separated two major tumor groups, for which patients in the group with high PDK2 and low KLF3 expression had the lowest survival probability." (PMID 17054779, 2006). "Multivariate analysis identified MRPL11, TBX3, and PDK2 expression as independent prognostic gene variables, whereas only tumor volume was identified in a model containing the clinical variables." (PMID 17054779, 2006). "Tumor volume and PDK2 expression remained independent prognostic variables when both clinical and gene variables were considered." (PMID 17054779, 2006). "In the context of OS, inhibiting PDK2 was found to slow tumor growth and progression." (PMID 40070565, 2025). "Although accumulating evidence has shown the pivotal roles of PDK2 in tumor cell proliferation, migration and drug resistance, how PDK2 is regulated in cancer cells is largely unknown." (PMID 38778217, 2024). "Thus PDK2 inhibits PD-L1 expression and promotes anti-tumour effects (blocking PD-1/PD-L1 dependent tumour antigen-specific CD8+ T cell apoptosis)." (PMID 37397243, 2023). "Additionally, has_circ_0005397 down-regulation reduces tumor growth by lowering PDK2 and increasing miR-326." (PMID 36672755, 2022). "Inhibiting PDK1 and PDK2 in such environments reduced the formation of tumor spheroids." (PMID 36474273, 2022). "PDK2 was highly expressed in HCC tumor tissues relative to matching normal tissues." (PMID 33817300, 2021). "Since PDK2 is broadly present in most tissues, targeting PDK2 may be a more important and efficient way to kill tumor cells and overcome chemoresistance." (PMID 31597953, 2020). "The miR-422a–PDK2 axis inhibits tumor progression mainly through metabolic reprogramming." (PMID 29725130, 2018). "In addition to repressing aerobic glycolysis of GC tumor cells, the miR-422a–PDK2 axis promoted lipogenesis and elevated the production of ROS, leading to rapid hypophosphorylation of retinoblastoma protein (RB) and cell cycle arrest." (PMID 29725130, 2018). "However, Western blot analyses for two PDK isoenzymes, PDK-1 and PDK-2, showed less expression in c4 compared with WT tumours." (PMID 21612605, 2011).
tumor (continued). "PDK1 and PDK2 silencing could reduce the tumor sphere formation of HNC cells." (PMID 36474273, 2022). "PDK2 and PDK3 protein expression in tumor cells correlated with lower patient overall survival, whereas PDK1 protein expression correlated with higher patient survival." (PMID 37147361, 2023). "PDK1, PDK2, and PDK3 play a role of tumor promoters, while PDK4 plays a different role in tumor aggressiveness depending on the cancer origin." (PMID 36474273, 2022). "Gene expression data of microdissected stroma from normal breast and TNBC31 showed significant downregulation of PDK2 and low levels of PDK1, PDK3 and PDK4 in the tumour stroma similarly to our CAFs." (PMID 35760868, 2022). "The tumor spheroid-forming capability, motility, CSC genes, and multidrug-resistant genes were downregulated in PDK1 and PDK2 silencing CSCs." (PMID 36474273, 2022). "In this study, in addition to PDK1, we further found that PDK2 silencing reduced the stemness features of HNC CSCs, including tumor sphere formation ability, motility, CSC genes, and multidrug-resistant genes (ABC)." (PMID 36474273, 2022). "The hidden links between PDK1, PDK2, PDK3, and PDK4 expression and tumor-infiltrating immune cells in GC were assessed by the TIMER database." (PMID 34220962, 2021). "No significant statistical relationship existed between PDK1, PDK2, and PDK3 expression and tumor grade (P = 0.257, P = 0.395, P = 0.544)." (PMID 34220962, 2021). "A significant decrease in the expression of circ_0091579 and PDK2 protein was found in the sh-circ_0091579 group, whereas the interference of circ_0091579 notably increased the expression of miR-1287 in HCC tumor tissues." (PMID 33817300, 2021). "Tumor tissues with high c-Met expression level in TCGA have increased expression of H6PD, PDK2, PDK4, PDPR, PKLR, SLC2A2 genes whereas decreased expression of GYS1, HK1, HK2, SLC2A1, significantly." (PMID 34059694, 2021). "Earlier studies indicate that miR-214 plays a tumor suppressor role by inhibiting proliferation and migration of HCC cells through targeting pyruvate dehydrogenase kinase 2 (PDK2) and plant homeodomain finger protein 6 (PHF6)." (PMID 31640265, 2019). "The impact of miR-422a and PDK2 on ROS levels could be partially abrogated via modulation of de novo lipogenesis, emphasizing the crucial effects of reprogramming metabolism, not only aerobic glycolysis but also other metabolic pathways, including lipogenesis, in tumorigenesis and tumor progression." (PMID 29725130, 2018). "Previous studies have demonstrated that PDK2 plays a critical role in OXPHOS, glycolysis, and tumor maintenance of cancer cells." (PMID 28881758, 2017). "One group was associated with rapid proliferation, oxidative phosphorylation, invasiveness, and tumor size (MRPS23, MRPL11, CKS2, LSM3, TBX3, MSN) and another with hypoxia tolerance, anaerobic metabolism, and high lactate content (PDK2, KLF3)." (PMID 17054779, 2006). "PDK2 phosphorylates pyruvate dehydrogenase (PDH) to inhibit the activity of mitochondrial pyruvate dehydrogenase complex, which reduces mitochondrial pyruvate metabolism, suppresses reactive oxygen species production, and promotes xenograft tumor growth." (PMID 38778217, 2024). "Importantly, we found a significant positive correlation of PDK2 and PDK3 immunostaining with lower overall survival (p = 0.021 and p = 0.022), and a positive correlation of PDK3 expression with higher tumor grade (p = 0.038)." (PMID 37147361, 2023). "The third test case involved pyruvate dehydrogenase kinase 2, a member of the GHKL ATPase/kinase superfamily that has a central control role upon cellular energy metabolism and is involved both in metabolic and neoplastic diseases." (PMID 36835004, 2023). "The expression of PDK2 and PTEN is lower in tumor than in normal." (PMID 35634241, 2022).
tumor (continued). "Although PDK1 and PDK2 have similar biological functions in the chemoresistance and tumor progression of HNC, we found that only PDK2 was significantly elevated in the advanced stage of HNC and that PDK2 silencing predominantly inhibited the proliferation and colony formation abilities of HNC cells." (PMID 36474273, 2022). "PDK2 and PDK4 expression had shown a great correlation with tumor stage (P = 0.00289, P = 0.00431)." (PMID 34220962, 2021). "O-GlcNAcylation repressed the TCA cycle by enhancing the transcriptional expression of PDK2, which inhibited PDH-mediated mitochondrial pyruvate metabolism, thereby reducing reactive oxygen species (ROS) production and promoting cell proliferation and tumor growth." (PMID 38778217, 2024). "RORα was shown to inhibit pyruvate dehydrogenase kinase 2 (PDK2) expression and phosphorylation, thereby promoting aerobic glycolysis rather than oxidative phosphorylation, whereas reduced RORα expression in tumor cells promotes oxidative phosphorylation and tumor cell growth." (PMID 26878025, 2015).
cancer (37 papers, 2011 to 2025). A tumor composed of atypical neoplastic, often pleomorphic cells that invade other tissues. "Pyruvate dehydrogenase 2 (PDK2) was highly expressed across various tumors and is closely associated with the malignant phenotypes of cancers." (PMID 40070565, 2025). "What's more upregulation of PDK2 is associated with metabolic reprogramming and chemoresistance of cancer cells, so it is also worth studying whether DUXAP8 can modulate these phenotypes of HCC cells." (PMID 32022476, 2020). "Because sirolimus only inhibits mTORC1 and the discovery of mTORC2 as PDK2 highlights some remarkable questions about the usage of sirolimus derivatives in cancer therapy." (PMID 36109789, 2022). "Studies have reported that PDK1 and PDK2 inhibition suppresses the growth, motility, and drug resistance of cancer cells." (PMID 36474273, 2022). "Our results showed that PDK2 expression increase was much lesser in cancer cells under hypoxia, herein indicating the greater PDH activity in cancer cells than that in non-cancerous cells." (PMID 26956544, 2016). "Thus, regulating PDK2 to alter macrophage metabolism and influence their activation or polarization has considerable therapeutic potential in cancer and inflammatory diseases." (PMID 38193078, 2023). "Moreover, we found that miR-146b-3p is a key inhibitor to target PDK2 to suppress Akt signaling pathway, Previous findings showed that cancer cells increase endothelial cell tube formation and survival by activating the PI3K/Akt signaling pathway." (PMID 36793126, 2023). "PDK2 overexpression reduced the anti-cancer effects of miR-326 in HCC." (PMID 36672755, 2022). "This is in line with the proposed oncogenicity of PDK2 overexpression in other cancer types." (PMID 35692804, 2022). "The upregulation of PDK2 in HCC cell lines declined the anti-cancer roles of miR-326." (PMID 36672755, 2022). "Although PDK1 and PDK2 have been previously proposed as cancer drug targets, our findings suggest that PDK4 may function as a metabolic tumor suppressor." (PMID 25379179, 2014). "Therefore, elevated PDK2 levels may have more prominent effects in the cancer aggressiveness of HNC." (PMID 36474273, 2022). "The HPV E6 oncoprotein also positively regulates pyruvate dehydrogenase kinase 2 (PDK2) and subsequently negatively regulates pyruvate dehydrogenase (PDH), thereby lowering the acetyl CoA level and shifting the metabolism towards lactate production, another hallmark of cancer." (PMID 33807087, 2021). "Importantly, we further demonstrated that the mir-422a–PDK2 axis also influenced another metabolic pathway, de novo lipogenesis in cancer cells, and that it subsequently affected reactive oxygen species (ROS) and RB phosphorylation levels, ultimately resulting in cell cycle arrest in G1 phase." (PMID 29725130, 2018). "There are a couple of key enzymes and transporters regulating cancer cells glycolysis, such as GLUT1, PKM2, pyruvate dehydrogenase kinase isoform 2 (PDK2), and Lactate dehydrogenase A (LDHA)." (PMID 35978828, 2022). "PDK1, PDK2, PDK3, PDK4, PDP2, and PDPR genes can regulate the glucose metabolism and glycolysis of cancer cells." (PMID 34199666, 2021). "We found that DCA reduced the protein abundance of PDK1 in MDA-MB-231 and PC-3 cancer cells and the protein abundance of PDK1 and PDK2 in L6 myotubes." (PMID 34445316, 2021). "While PDK1 is less sensitive to DCA than PDK2 or PDK4 (PDK2 > PDK4 > PDK1 > PDK3), DCA reduced the abundance of PDK1 in cancer cells and fibroblasts, indicating that inhibition is not the only mechanism by which DCA reduces the PDK1 function." (PMID 34445316, 2021).